MMP24OS (MMP24 opposite strand)
Synonyms: MMP24-AS1
Gene: Protein-coding gene on chromosome 20 (35,201,745 to 35,278,131, reverse strand). Ensembl gene ENSG00000126005.
Diseases named in the same sentence as MMP24OS in open-access papers:
MMP24OS is named in the same sentence as 1 disease in open-access papers, as found by Europe PMC text mining. Sharing a sentence is not in itself a finding about the gene and the disease.
MMP24OS shares sentences with these, for which no sentence is quoted: tumor (1 paper).